F8A1 (coagulation factor VIII associated 1)
Description:
RAB5A effector molecule that is involved in vesicular trafficking of early endosomes. Mediates the recruitment of HTT by RAB5A onto early endosomes. The HTT-F8A1/F8A2/F8A3-RAB5A complex stimulates early endosomal interaction with actin filaments and inhibits interaction with microtubules, leading to the reduction of endosome motility.
Synonyms: HAP40; DXS522E; F8A
Gene: Protein-coding gene on chromosome X (154,886,355 to 154,888,061, forward strand). Ensembl gene ENSG00000288722.
Subcellular location: Cytoplasm; Nucleus; Early endosome; Nucleus, nuclear body
Gene Ontology:
Molecular function: protein binding
Biological process: negative regulation of proteasomal protein catabolic process; endosomal transport; vesicle cytoskeletal trafficking
Cellular component: cytoplasm; early endosome; nucleus; nuclear body
Homologues: Orthologues: chimpanzee F8A1 (99% identical), rat F8a1 (86% identical), mouse F8a (85% identical), tropical clawed frog f8a1 (53% identical), zebrafish f8a (51% identical), Drosophila melanogaster Hap40 (22% identical). Paralogues in human: F8A2 (100% identical), F8A3 (100% identical).
Diseases named in the same sentence as F8A1 in open-access papers:
F8A1 is named in the same sentence as 4 diseases in open-access papers, as found by Europe PMC text mining. Sharing a sentence is not in itself a finding about the gene and the disease. The quoted sentences say what the papers report.
cancer (1 paper, 2021). A tumor composed of atypical neoplastic, often pleomorphic cells that invade other tissues. "However, despite their proximity and encoding the identical protein, F8A1, F8A2 and F8A3 each have highly distinct patterns of expression across the thousands of samples of tissues and cancers in the TCGA/GTEx dataset, indicating they may participate in different or overlapping biological scenarios." (PMID 33972602, 2021).
F8A1 also shares sentences with these, for which no sentence is quoted: pleural tumors (2 papers); Huntington disease (1); type 1 diabetes (1).